CRP (C-reactive protein)
Diseases named in the same sentence as CRP in open-access papers (continued):
Sharing a sentence is not in itself a finding about the gene and the disease.
leukocytosis (continued). "Our data highlight the association between important factors such as younger age, positive blood culture, use of gentamycin, laboratory parameters (high CRP, leukocytosis, thrombocytopenia), and higher SOFA score and the incidence of higher stages of AKI." (PMID 39597864, 2024). "Laboratory tests revealed elevated C-reactive protein levels (7.055 mg/dL) and leukocytosis resulting from a left gluteal abscess." (PMID 38957240, 2024). "In the course of AC, the main laboratory findings are leukocytosis and increased C-reactive protein." (PMID 38731224, 2024). "Significant leukocytosis and high CRP values measured on day 1 were encountered in group B, with ROM < 18 h (p < 0.001)." (PMID 38255436, 2024). "Regarding paraclinical studies, 94 (56%) patients presented leukocytosis, 132 (78.6%) neutrophilia, and in 20 (17.9%) patients, the CRP test was reactive." (PMID 39347224, 2024). "The general blood test (GBT) showed leukocytosis and elevated C-reactive protein (CRP) levels, indicative of intoxication syndrome." (PMID 39639977, 2024). "Age, mechanical ventilation (MV) requirement, leukocytosis, neutrophilia, high c-reactive protein level, NLR, and CLR showed a statistically significant association with mortality in the univariate analysis." (PMID 38421951, 2024). "A blood test showed leukocytosis with an elevated C-reactive protein level (11.801 mg/dL), indicative of a urinary tract infection (UTI)." (PMID 38957240, 2024). "Blood test showed leukocytosis, especially neutrophilia and monocytosis and increased levels of c-reactive protein and procalcitonin." (PMID 38443922, 2024). "The most common results of laboratory changes during pregnancy confirmed with COVID-19 were C reactive protein, lymphopenia, leukocytosis, and thrombocytopenia." (PMID 39280542, 2024). "Initial investigations showed elevated C-reactive protein (CRP), increased serum creatinine and blood urea nitrogen, leukocytosis, neutrophilia, and increased lactate dehydrogenase (LDH)." (PMID 39597031, 2024). "Laboratory markers as leukocytosis or elevated C-reactive protein are helpful for arising suspect of this pathology, especially for the complicated forms." (PMID 38472633, 2024). "Initial blood tests confirmed leukocytosis, anemia, elevated fecal calprotectin (FC), and C-reactive protein (CRP) levels." (PMID 38741148, 2024). "Her blood investigations demonstrated evidence of leukocytosis and high c-reactive protein (CRP) levels." (PMID 38500931, 2024). "Leukocytosis and CRP serum values recorded on the first day were significantly higher in the B2 subgroup compared to the A2 subgroup (p < 0.05)." (PMID 38255436, 2024). "Initial labs showed leukocytosis, thrombocytopenia, elevated total bilirubin, elevated alkaline phosphatase, and increased C-reactive protein (CRP)." (PMID 39350858, 2024). "The laboratory investigations revealed leukocytosis and elevated C-reactive protein (CRP) levels, meaning inflammation was present." (PMID 38414046, 2024). "Laboratory investigations showed leukocytosis, anemia, thrombocytosis, and elevated inflammatory markers including high CRP, ESR, and procalcitonin." (PMID 39877780, 2024). "The primary endpoint was the incidence of PIS, defined as the presence of fever (≥38 °C), leukocytosis, and elevated C-reactive protein (CRP) within 30 days postprocedure." (PMID 39407997, 2024). "Laboratory tests conducted upon her arrival showed leukocytosis and elevated C-reactive protein (CRP) levels." (PMID 39850468, 2024). "The patient had a leukocytosis of 23.9, a neutrophilia of 90.3%, and biological inflammatory syndrome (CRP of 88.52 mg/L, fibrinogen of 877 mg/dL, and ESR of 78 mm/h)." (PMID 39001281, 2024). "A CT scan conducted two days before his visit showed foraminal stenosis, and laboratory tests indicated leukocytosis (12.95 × 109/L) and elevated CRP (2.08 mg/dL)." (PMID 39594253, 2024).
leukocytosis (continued). "Leukocytosis was observed in 12 (33%) patients, whereas high c-reactive protein and high erythrocyte sedimentation rate presented in 29 (81%) and 11 (31%), respectively." (PMID 38467940, 2024). "The general environment common to both states is low-grade inflammation, characterised by peripheral leukocytosis and elevated C-reactive protein (CRP) in serum." (PMID 38255279, 2024). "In the acute phase, laboratory examination of MKD patients reveals leukocytosis, elevated C-reactive protein (CRP), and erythrocyte sedimentation rate (ESR)." (PMID 38183017, 2024). "Infectious symptoms such as fever were reported in 11.6% (n = 15) of cases, and leukocytosis was observed in 41.9% (n = 54), whereas C-reactive protein elevation was a common finding in 94.8% (n = 127) of patients." (PMID 38731085, 2024). "Laboratory tests showed a disrupted biological profile with significant inflammatory and infectious syndromes (leukocytosis = 15,200/mm3 and CRP = 250 mg/L)." (PMID 39423582, 2024). "Laboratory findings revealed leukocytosis (13700 103/μL), severe anemia (hematocrit: 26%; hemoglobin: 8.8 g/dL), electrolyte abnormalities, and elevated C-reactive protein (15.9 mg/dL)." (PMID 39135818, 2024). "Elevated CRP was observed in four (12%) patients, while elevated ER and leukocytosis were noted in three (9%) patients." (PMID 39336447, 2024). "Along with leukocytosis and elevated C-reactive protein levels, the urine culture indicated an infection with Escherichia coli." (PMID 38414046, 2024). "Laboratory findings, including complete metabolic panel and complete blood count, showed slight leukocytosis at 12.0 k/μL, normal electrolytes, and elevated c-reactive protein (CRP) at 4.3 mg/dL." (PMID 38656564, 2024). "The initial investigation revealed a slight elevation of C-reactive protein and leukocytosis with neutrophilia." (PMID 39092363, 2024). "Laboratory investigations confirm the diagnosis is of limited efficacy, as leukocytosis and elevated C-reactive protein are present only in 20% and 10% of these cases." (PMID 37278935, 2024). "The most common indication for obtaining BCs overall was increased CRP (1647/2206 BC sets, 74.7%), followed by either leukocytosis, leukopenia, or neutropenia (1432/2206, 64.9%)." (PMID 39596775, 2024). "Peripheral blood revealed leukocytosis with increased neutrophils and elevated C-reactive protein levels." (PMID 39376867, 2024). "In cases of significant leukocytosis or elevated C-reactive protein (CRP) levels, a short course of broad-spectrum antibiotics was initiated to rule out any potential infectious component." (PMID 39407997, 2024). "This table summarizes the laboratory results of a patient with right lower lobe pneumonia, including mild leukocytosis, elevated C-reactive protein (CRP), and increased erythrocyte sedimentation rate (ESR), all indicative of an acute inflammatory response." (PMID 39759626, 2024). "Blood examinations showed leukocytosis and a marked increase of C-reactive protein to 22 mg/dL as well as a moderate increase of bilirubin and liver enzymes." (PMID 39741600, 2024). "Overall, most common laboratory findings were increased CRP, mild leukocytosis, especially neutrophilia and elevated D-dimer." (PMID 37500944, 2024). "Physical examinations showed stiffness of the neck, laboratory tests suggested leukocytosis (27.2 × 109/L), increased serum level of C-reactive protein (184.7 mg/L) and total bilirubin (44.6 μmol/L)." (PMID 38440138, 2024). "Her laboratory findings were remarkable for leukocytosis, thrombocytosis, anemia, and high C-reactive protein (CRP)." (PMID 39877780, 2024). "Laboratory tests showed leukocytosis (24,200/μL), creatinine 1 mg/dL, C-reactive protein 20.77 mg/dL, and lactate 0.6 mmol/L." (PMID 39687832, 2024). "Blood tests revealed leukocytosis (11,000 cells/mL) with neutrophil predominance (85%) and elevated C-reactive protein (CRP) (48.49 mg/L)." (PMID 38534984, 2024).
leukocytosis (continued). "Labs showed leukocytosis (white blood cells of 25.01x10^9/L), neutrophilia (24.73x10^9/L), elevated C-reactive protein (CRP) (140mg/L), increased procalcitonin (PCT) (15.57ng/ml), reduced PaO2/FiO2 (163.5 mmHg), and high lactic acid (2.8 mmol/L)." (PMID 39351355, 2024). "The clinical presentation of this condition is often nonspecific, with patients typically experiencing fever, chills, and upper abdominal pain, while laboratory results frequently show leukocytosis, anemia, and elevated CRP levels." (PMID 39188446, 2024). "Laboratory tests performed on admission showed leukocytosis with granulocytosis, elevated C-reactive protein (CRP) levels, a downward trend in aminotransferase levels, and normalization of cardiac parameters." (PMID 39767938, 2024). "Laboratory investigations showed a significant elevation in serum lipase levels, 24 times above the normal range, along with leukocytosis (16,000/mm3) and an elevated C-reactive protein (CRP) level of 460 mg/L." (PMID 39423582, 2024). "Blood tests showed leukocytosis and elevated C-reactive protein (CRP) levels indicative of inflammation." (PMID 38178812, 2024). "The patient had a leukocytosis of 13.1, a neutrophilia of 9.9, and biological inflammatory syndrome (CRP of 61.8 mg/L, fibrinogen of 608 mg/dL, and ESR of 44 mm/h)." (PMID 39001281, 2024). "Positive laboratory findings indicated leukocytosis (17.55 × 109/L), anemia (96 g/L), thrombocytosis (611 × 109/L), elevated C-reactive protein (CRP) level (28.9 mg/L), and reduced sodium concentration (132 mmol/L)." (PMID 39151496, 2024). "While leukocytosis and anemia followed by increased C-reactive protein (CRP) along with elevated alkaline phosphatase were the most common laboratory findings." (PMID 39188446, 2024). "The leukocytosis and elevated CRP levels observed before decannulation in this study reflect proinflammatory conditions induced by the ECMO circuit, which was similar to the results of other studies." (PMID 39797141, 2024). "Significantly more patients were treated with antibiotics if they were diagnosed with UTI, had premature rupture of membranes for more than 18 h, or had leukocytosis, neutrophil predominance, or a higher level of C-reactive protein." (PMID 38333085, 2024). "Clinical (fever, leukocytosis, elevated basal energy expenditure) or biochemical (CRP, albumin and prealbumin) indicators can be used, which can help to assess the presence of inflammation." (PMID 38337661, 2024). "In a case study, researchers observed that infected pregnant women exhibited leukocytosis, lymphopenia, an increased neutrophil ratio, elevated d-dimer levels, elevated C-reactive protein (CRP), and raised lactate dehydrogenase (LDH)." (PMID 39659767, 2024). "Blood test abnormalities were noted in 50% of cases, mainly mild to moderate leukocytosis and elevated C-reactive protein." (PMID 38680784, 2024). "Still, leukocytosis, high C-reactive protein (CRP), severe acidosis, renal failure, impaired Liver Function Test (LFT), and thrombocytopenia are findings in favor of transmural necrosis." (PMID 39159593, 2024). "Laboratory tests revealed leukocytosis with neutrophil predominance, elevated C-reactive protein (CRP) levels, and hyperferritinemia." (PMID 38813312, 2024). "Leukocytosis and high levels of CRP cases should be considered infectious complications such as cervical abscess and pneumonia." (PMID 39158760, 2024). "Blood analysis revealed leukocytosis with neutrophilia (white blood cell count 21790/μL, neutrophils 13728/μL, lymphocytes 6057/μL), an elevated C-reactive protein (CRP) level of 100.5 mg/L and a procalcitonin level of 0.29 ng/mL." (PMID 39735087, 2024). "There was heightened concern for appendicitis given right lower quadrant pain, leukocytosis, and elevated CRP." (PMID 39634689, 2024).
leukocytosis (continued). "Some predictors of mortality associated with inflammatory biomarkers, including the erythrocyte sedimentation rate (ESR), leukocytosis, C-reactive protein (CRP) and procalcitonin, have been shown to indicate a poor prognosis in patients with IE." (PMID 39346087, 2024). "Inflammatory markers, such as leukocytosis, increased C-reactive protein are present in both conditions, but C-reactive protein is more increased in TC than in AMI." (PMID 38360558, 2024). "Lab results often seen in GBV patients include leukocytosis, a raised C-reactive protein (CRP), and normal liver transaminases." (PMID 39205772, 2024). "Blood examinations showed leukocytosis and a marked increase of C-reactive protein (CRP) to 22 mg/dL as well as a moderate increase of bilirubin and liver enzymes." (PMID 39741600, 2024). "Plans to close the chest were again delayed when a low-grade fever, rising CRP, and leukocytosis recurred." (PMID 39483118, 2024). "Laboratory findings often reveal increased levels of inflammatory markers like ESR, CRP, and leukocytosis." (PMID 39569262, 2024). "Recently found data also suggested that pregnant patients' infected with SARS-CoV-2 disease can present with laboratory changes during pregnancy involving changes in C-reactive protein, lymphopenia, leukocytosis, and thrombocytopenia." (PMID 39280542, 2024). "Laboratory investigation revealed an increased C-reactive protein (CRP) level, procalcitonin level, and leukocytosis." (PMID 39569243, 2024). "Laboratory investigations were unremarkable except for leukocytosis of 14.6, high ferritin of 402 ng/mL, milady elevated liver enzymes, and high C-Reactive Proteins (CRP) of 133 mg/L. An abdomen ultrasound was done and showed enlarged liver measuring 15.3 cm." (PMID 39371885, 2024). "The laboratory workup revealed ongoing inflammation, with a progressive increase in the CRP levels (156 mg/L) and leukocytosis marked by neutrophilia." (PMID 39330780, 2024). "Laboratory results showed elevated CRP (3.2 mg/L), leukocytosis (14.8 x 103 white blood cells/μL), and thrombocytosis (587 x 109 platelets/L)." (PMID 39569262, 2024). "Leukocytosis and raised C-reactive protein (CRP) are also often observed in PES and can lead to overtreatment with intravenous antibiotics and hospital admission." (PMID 38233575, 2024). "Regarding the laboratory finding among our studied cases, we found that 23 (14%) had raised NLR, 123 (75%) cases had positive CRP, and 148 (90.2%) cases had leukocytosis." (PMID 36472649, 2023). "These patients experienced fever, abdominal pain, elevated C-reactive protein levels, and leukocytosis 1–3 days after DEB-TACE." (PMID 38041083, 2023). "Accurately determining the diagnosis of appendicitis is currently immensely dependent on the inflammatory biomarkers of leukocytosis and CRP taken from the blood." (PMID 37047015, 2023). "Up to 60% of the patients had elevated CRP (>5 mg/L), and 50% had leukocytosis greater than 10,000/μL." (PMID 37371691, 2023). "While laboratory tests were within the normal range, mild leukocytosis, anemia, and C-reactive protein(CRP) = 3 + were noted." (PMID 37828451, 2023). "Previous studies have reported leukocytosis in 26% women, lymphopaenia in 33% and raised C reactive protein levels in 49% women." (PMID 36877672, 2023). "It is remarkable that elevated infection-related indicators, such as leukocytosis, elevated CRP, elevated D-dimer level, and anemia, were observed, according to previous literature." (PMID 37565858, 2023). "Laboratory investigations showed elevated C-reactive protein (282 mg/L), leukocytosis (14.8 × 109/L) with neutrophilia (11.6 × 109/L), anemia (Hb 100 g/L), and thrombocytosis (404 × 109/L)." (PMID 37575996, 2023). "On admission, leukocytosis, elevated c-reactive protein, modified coagulation tests (due to ongoing anticoagulation treatment), and a mild elevation of the D-dimer tests were detected." (PMID 37510971, 2023).
leukocytosis (continued). "We found several known risk factors for SBIs, such as the male gender, an age < 1 month, leukocytosis, and an elevated CRP; however, in conjunction with respiratory symptoms or a positive virus test, the risk of SBIs decreased." (PMID 37510751, 2023). "CRP retained its independent association with OS in multivariate analysis in the presence of other adverse prognostic factors such as leukocytosis, thrombocytopenia, and the presence of circulating blasts, indicating an independent prognostic impact of CRP." (PMID 36441359, 2023). "Nevertheless, these findings were not correlated with the presence of significantly different values of inflammatory parameters (CRP and leukocytosis) and an increase in body temperature throughout the seven-day observation period." (PMID 36839578, 2023). "The blood panel of the participants showed leukocytosis, with lymphopenia (characteristics of the COVID-19 infection) and increased inflammatory markers CRP, D-dimer, ferritin, and IL-6." (PMID 38313184, 2023). "Leukocytosis with a white blood cell count of > 20,000/μL and C-reactive protein > 200 mg/L were observed in these four cases, which were accompanied by abdominal pain with or without low-grade fever." (PMID 38041083, 2023). "Leukocytosis, elevated CRP values, and accelerated sedimentation are always found in patients with myocarditis, but their diagnostic value is low due to their presence in many other diseases." (PMID 37835816, 2023). "There were significantly more leukocytosis, neutrophilia, band forms, and lymphopenia among cases, as well as higher C-reactive protein values (CRP)." (PMID 37368746, 2023). "Regarding the discharge from the OS, blood tests revealed leukocytosis and a C-reactive protein (CRP) concentration level of 2.5 mg/dL, and ESR increased to 87 mm/h." (PMID 36604664, 2023). "Leukocytosis (>10,000/mL) was seen in 12 (80%) of 15 patients and CRP was high in all 13 patients (100%) who were measured." (PMID 37189509, 2023). "Higher values of preoperative CRP and leukocytosis were observed in patients with CF compared to the rest of the study group (4.4 ± 5.76 mg/dL versus 1.31 ± 2.22 mg/dL, p < 0.05; 15.9 ± 6.24 × 103/μL vs. 10.65 ± 3.17 × 103/μL, p < 0.001, respectively)." (PMID 36839578, 2023). "The laboratory values showed that almost 20% of the patients had elevated C-reactive protein (CRP) levels and 45% had leukocytosis." (PMID 37629364, 2023). "Blood tests often show leukocytosis, increased red sedimentation, and elevated c-reactive protein (CRP) levels." (PMID 37444559, 2023). "Upon hospital admission, 30.3% of patients had hyponatremia, 28.1% had acute renal failure, 71.9% had CRP above reference values, 71.2% had a hemoglobin level below normal and 34.7% leukocytosis." (PMID 38100603, 2023). "They reported tachycardia in 14% (> 100 bpm), fever in 7% (≥ 38 °C), leukocytosis in 14% (> 15,000), and high CRP in 28% (> 2 mg/dL), which appeared to be more strongly associated with the event." (PMID 37023210, 2023). "A recent meta-analytic study disclosed that CRP has been found to be the most reliable marker (AUC = 0.8), together with leukocytosis (0.77) and PCT (0.77)." (PMID 37296721, 2023). "His laboratory studies revealed moderate leukocytosis with a bandemia, mild hyponatremia, and elevated serum inflammatory markers, namely the C-reactive protein (CRP) and the erythrocyte sedimentation rate (ESR)." (PMID 36859322, 2023). "Hypotension, tachycardia, tachypnea, elevated CRP, thrombocytopenia, leukocytosis, band forms, urea, and bilirubin remained significantly different in multivariate analysis between cases and controls." (PMID 37368746, 2023). "The symptoms of the inflammatory process (e.g., fever) and the main laboratory findings (e.g., leukocytosis, CRP and ESR increase) are common in many different types of inflammation." (PMID 37296737, 2023).